CD4 (CD4 molecule)
Diseases named in the same sentence as CD4 in open-access papers (continued):
Sharing a sentence is not in itself a finding about the gene and the disease.
infection (continued). "CD4+ and CD8+ T-cells and B-cells play important roles in fighting infection and cancer." (PMID 30911684, 2019). "In conclusion, this study indicated that S. japonicum infection could induce TLR7 expression in both CD4+ and CD8+ T cells of the MLN in C57BL/6 mice, and importantly, the alteration of TLR7 mediates T cell response in the early phase of infection." (PMID 31930147, 2019). "This study demonstrated that infection with Mtb activates an antigen-specific, polyfunctional Th-1 response as the magnitude of PPD-specific IFN-γ+ IL-2+ TNF-α+ polyfunctional CD4+T-cells was greatest in the LTBI group (P = 0.0002) in comparison with the HC group." (PMID 31105706, 2019). "Similar levels of infection were observed when non-activated CD4+ T cells were first isolated from PBMCs (data not shown)." (PMID 30943397, 2019). "Similarly to what occurs in other infections by intracellular bacteria, IFN-γ-producing CD4 T helper-1 (Th1) cells and natural killer T cells (NKT) mediate protective immunity against Ehrlichia." (PMID 31134081, 2019). "Our results demonstrate that vaccination with HK-fbp1 can provide protection against infection with C. neoformans even in the absence of CD4+ T cells." (PMID 31772051, 2019). "This infection pathology was thought to be CD4 T cell dependent because Th17 CD4 T cells expanded in the absence of IFNγ." (PMID 30873151, 2019). "Finally, antibody-mediated blocking of IFNAR, followed by intravaginal infection, enables the virus to spread systemically despite increased frequency of tetramer-specific CD8 T cells and total CD4 T cells in the lower female reproductive tract." (PMID 31382545, 2019). "When the immune system starts to recover, it fights to reduce viral levels, but CD4 counts do not usually recover to levels similar to pre-infection levels." (PMID 30344234, 2018). "Thus, we analyzed co-expression of ICOS and T-bet by CD4+ and CD8+ T cells during blood stage PbA infection." (PMID 29892278, 2018). "In addition, defects in the ability of adult CD4+ T cells to migrate to a draining lymph node in old mice have recently been reported, suggesting that age-related changes in the environment of old mice might lead to reduced CD4+ T cell responses upon immunization or infection." (PMID 29864157, 2018). "The majority of HCV-infected individuals do generate a relatively broad CD4 and CD8 T cell response early on after infection that may afford partial control of viremia." (PMID 30002657, 2018). "Also, and as detected after stimulation with NH36, the frequencies of CD4+TNF-α+ and CD4+TNF-α+IFN-α T cells were still higher in infected controls and only increased by the F3-vaccine, on day 28 after infection." (PMID 29867949, 2018). "This, together with the increase in frequency of activated CD4+ cells and significant decrease in % CD8+ cells after 7 days, suggests that MPA promotes infection by increasing the frequency of infectable cells while concomitantly decreasing the frequency of cytotoxic cells." (PMID 29698514, 2018). "In addition, CD4+T, CD8+T, and NK cell counts were significantly lower from d 1 to 14 in those patients with infection." (PMID 28877956, 2018). "The same result was obtained at later time points post infection in the spleen with increased CD11a+CD49d+ CD4 T cells expressing KLRG1 in CD11ccre+, but not LysMcre+ mice compared to Cre- controls at day 21 and day 40 p.i." (PMID 30044874, 2018). "We also did not detect infection in cis-exposed CD4+ T cells at the low MOI (10−3), with the exception of those for one participant (SN3)." (PMID 29643243, 2018). "In a model of herpes simplex virus-2 (HSV-2) infection, where thymidine-kinase defective (TK−) HSV-2 was used to avoid neurovirulence, CD4 T cells infiltrated the female genital mucosa during infection and provided help for mobilizing cytotoxic effector CD8 T cells that cleared the infection." (PMID 30147701, 2018).
infection (continued). "Although upon infection P25 mice present a greater increase in the proportion of activated CD4+ T cells, there are no signs of in vivo higher production of IFNγ or of immunopathology in comparison to WT mice." (PMID 29499041, 2018). "While the uptake of infected T cell by macrophages was independent of the Env/CD4 interaction, the productive infection of macrophages following uptake of T cells would be dependent of this interaction, and also depended of the tropism of the viruses." (PMID 29515578, 2018). "Herpes simplex virus type 2 (HSV-2) is a common infection in human immunodeficiency virus (HIV) patients and may accelerate HIV progression by rising HIV viral load and decreasing CD4 count." (PMID 28688377, 2018). "Furthermore, the overall numbers of CD45+ cells and CD4+ and CD8+ T cells were significantly lower in the antibody-treated mice at the early (7 dpi) infection." (PMID 29410948, 2018). "Consequently, the depletion of CD4+ T cells in the gut during acute HIV and SIV infection is both more rapid and severe than peripheral blood." (PMID 30440043, 2018). "Because the absence of CCR4 increased the number of CD4+ cells in the lungs in the chronic phase of infection, we further evaluated the functional activity of CD4+ subsets." (PMID 30584243, 2018). "Purified immune B cells were not protective, while transfer of immune CD4+ T cells fully protects recipient naïve A129 mice from M766 lethal infection, indicating a crucial role of CD4+ T cells in the protective immune response to ZIKV." (PMID 30087337, 2018). "Infection did not affect the percentage of double positive memory T-cell (CD3+CD4+ CD8+) or NK cell (CD3−CD8+) populations." (PMID 30072754, 2018). "We develop a Bayesian statistical model to evaluate delay-to-diagnosis distributions in HIV patients without known infection date, based on viral sequence genetic diversity and longitudinal viral load and CD4 count data." (PMID 29945571, 2018). "We here report that human CD4+ T cells show activation-dependent upregulation of GLUT1, GLUT3, GLUT4, and GLUT6 mRNA as well as protein, and that GLUT protein expression is further enhanced upon infection of the cells with HIV-1." (PMID 29518929, 2018). "One possible mechanism for reduced numbers and function of these cells could be direct infection and destruction by HIV-1 itself, at least among those Vδ2 expressing CD4 and chemokine receptors CCR5 and CXCR4 or α4β7." (PMID 30219039, 2018). "At day 3 post infection, CD4 T cell depletion did not significantly impact the frequency of functional ILC1s." (PMID 29623077, 2018). "Because the median frequency of CD4 on Vδ1+ cells was less than 10% in each cohort, we did not pursue direct infection as a driver for the population level activation changes observed." (PMID 30405182, 2018). "Peripheral blood CD4+ T-cell counts moderately fluctuated, but did not decrease significantly over a prolonged period of infection." (PMID 30210504, 2018). "Ontak administration to DKO-hu HSC mice, followed by infection with HIV-R3A, reduced the levels of Tregs in blood, spleen, and mesenteric LN and increased the expression of HLA-DR, a marker of immune activation, on CD4+ and CD8+ T cells." (PMID 29706961, 2018). "Using this technique, groups have demonstrated that CD4+, CD8+, and MAIT cells control attenuated or virulent Francisella replication in macrophages, further underscoring the importance of these cell subsets during infection." (PMID 29682484, 2018). "For example, in the absence of infection 1 week old mice were reported to have significantly reduced numbers of splenic CD4+ and CD8+ cells, as well as lung CD8+ cells, compared to mice that were 2 weeks or older." (PMID 30258820, 2018). "Others have also shown a reduction in necessary inflammatory mediators and in the numbers of cytotoxic CD8+ T cells present at the infection site in the absence of CD4+ T cells." (PMID 29616390, 2018).
infection (continued). "Cross-reactive and antigen-non-specific T cell immunity appears to not contribute to the immediate defense provided by X-31ca, as the vaccination with X-31ca prior to infection with RSV did not alter the compositions of CD4 and CD8 cells in the lungs." (PMID 29445364, 2018). "Although the lower FRT does not contain MALT in the steady state, both CD8+ and CD4+ TRM cells can be established in the lower FRT following intravaginal infections, such as those mediated by herpes simplex virus type 2 (HSV-2)." (PMID 29904388, 2018). "Both CD4+ T-bet+ cells and CD4+ GATA-3+ cells significantly increased following intraportal inoculation of S. mansoni-eggs as well as after S. mansoni-cercariae infection." (PMID 29373600, 2018). "The mean duration of infection without any form of anti-retroviral therapy was 14.6 years with a substantial number (34%) still relatively heathy with CD4 counts above 500 cells/mL." (PMID 29664957, 2018). "Infection of TZM-bl cells by WT virus and clone 1 was similarly inhibited by CD4-Ig." (PMID 30125330, 2018). "Mice infected with T. spiralis demonstrated higher expression of PD-1 in the spleen CD4+ T cells than those without infection." (PMID 30093899, 2018). "Of note, vaccination with X-31ca prior to infection with RSV did not appreciably change the CD4 and CD8 T cell composition in the lungs." (PMID 29445364, 2018). "FIV requires an initial interaction with a primary binding receptor for infection, and binds to host cells through a high-affinity interaction of the envelope SU protein (gp95) with the CD134 surface molecule present on CD4+ lymphocytes and monocytes/macrophages." (PMID 29677122, 2018). "We observed that in this infection model, IFNγ produced in both the cKO and control mice by CD4+ T cells, CD8+ T cells and NKT cells were not altered." (PMID 30258450, 2018). "Within the lung, type 1 helper CD4+ T cells (TH1), distinguished by upregulated transcription factor T-box expressed in T cells (T-bet), secrete interferon-γ (IFN- γ) along with interleukin (IL)-2 at the site of infection." (PMID 29616390, 2018). "Surprisingly, CD4+ T cells isolated from SDLN of Curdlan-treated mice showed a transient trend toward a lower expression of the key transcription factor T-bet, known to define Th1 cells, and of the Th1 cytokine IFN-γ at day 10 after infection." (PMID 29535708, 2018). "CD4+ T cells can also form a VS-like structure with epithelial cells from the genital mucosa, which leads to transcytosis of HIV-1 through the epithelium and subsequent infection of stromal macrophages." (PMID 30055632, 2018). "Although the survival of Nur77 deficient CD4 TRM cells has not yet been assessed, it is likely that depending on the tissue, intercellular interactions or infection context, CD4 TRM cells are differentially dependent on antigen and T cell receptor signaling." (PMID 30386342, 2018). "We further observed that a vast majority of these AgExp CD4 and AgExp CD8 T cells were resident within the lung tissue (CD45i.v.Abneg) based on in vivo antibody labeling in IAV-nanovax vaccinated mice, similar to that observed following IAV-infection." (PMID 30233573, 2018). "However, SUN2 has also been demonstrated to be an essential host factor for promoting the infection of HIV-1 and HIV-2 in human primary CD4+ T cells and MDDCs." (PMID 29717016, 2018). "Given that the combined vector effectively primed peptide-specific CD4+ T cells in vivo, we addressed whether the FPM2e:NPL vector was also effective at stimulating protective immunity against infection." (PMID 30271406, 2018). "The relative infection and replication of HIV-1 in CD4+ ILC1s is comparable to that in CD4 T cells." (PMID 29304123, 2018). "We previously demonstrated that DC targeting via injection of anti-DC-SIGN antibodies into hSIGN mice induces strong and durable Ag-specific CD4+ and CD8+ T-cell responses capable of mediating protection against infection with OVA-expressing Listeria monocytogenes." (PMID 29662482, 2018).
infection (continued). "On the other hand, Th cells (CD4+) were found increased in spleen, PLN and MLN due to infection." (PMID 29921576, 2018). "Human and experimental mouse studies suggest that strong pro-inflammatory responses generated during blood-stage infection can inhibit productive GC and Tfh cell responses, and recent data suggest a role for PMIF in the suppression of CD4 T cell differentiation." (PMID 30006528, 2018). "Importantly, in this latter study, CD103 was observed on ~10% of CD4 TRM cells isolated from the human lung, which is in contrast to mouse models either at steady state or after infection." (PMID 30386342, 2018). "This is the traditional model to explain infection of resting CD4+ T cells by HIV and latency formation, but it is not the only model, nor an exclusive model." (PMID 30285810, 2018). "PC were isolated from mice 8 weeks after infection and cultured in the presence of either prostratin and SAHA, the most efficient inducers of latent EcoHIV in CD4+ cells, or TNF-α, an inflammatory cytokine that induces HIV expression in transformed human macrophages." (PMID 29879225, 2018). "trans infection of CD4+ T cells is believed to occur by two different, but not mutually exclusive, pathways following DC or MΦ exposure to virus: (i) exposure through rapid virus uptake via endocytosis into vesicles and (ii) after de novo infection." (PMID 29643243, 2018). "Several studies demonstrate that the CD4+ T cell response does not initiate until 10–14 days after infection and peaks at nearly 3 weeks after infection by M. tuberculosis in mice." (PMID 29868514, 2018). "However, the time of emergence of PFC responses against EBV lytic or latent antigens, differences between CD4+ and CD8+ T cell responses, and concurrent EBV loads in PBMC and plasma from acute to chronic stage of infection are not clearly understood." (PMID 29599759, 2018). "HS may be directly involved in the infection of CD4+ and/or CD4− cells, making it an ideal target for new anti-HIV therapies." (PMID 30555321, 2018). "Although we did not see a difference in CD4 or CCR5 surface expression by NP and PR MΦ, membrane fluidity alterations could decrease the function of CD4, CCR5, and DC-SIGN, thereby impacting cis infection." (PMID 29643243, 2018). "VSV-G receptor-mediated endocytosis does not result in efficient infection of resting CD4 + T cells due to limited endocytosis." (PMID 29654266, 2018). "To distinguish pre and post CD4 activity, we synchronized infection by spinoculation at 23°C, a temperature that allows for virus binding to CD4 but not for fusion, and added the bnAbs either before or after CD4 attachment." (PMID 29370298, 2018). "Overall, however, equivalent percentages of CD4+ and CD8+ T lymphocytes could produce infection of the virus-permissive cells." (PMID 30103427, 2018). "We conclude that CD4 T cell are not essential for cross-protection against A(H1N1)pdm09 during infection in this mouse model." (PMID 30356772, 2018). "The group receiving ART treatment since week 1 post-infection plus PH-797804 achieved the lowest frequency of immune activation markers in CD4+ and CD8+ T cells, although values did not return to baseline and remain approximately 2-fold higher." (PMID 30161247, 2018). "The HIV envelope protein gp120 binds to α4β7; however, a link between this interaction and the preferential infection of α4β7high CD4+ T cells has not been established." (PMID 30153309, 2018). "Hovewer, using an in vitro infection system, the authors found that CD32a was induced selectively in resting CD4 cells latently infected with HIV but not on those cells actively replicating HIV." (PMID 30341387, 2018). "A decrease in the frequency of CD4+Foxp3+ cells was found in the lungs of infected CCR4−/− mice at 15 and 70 days of infection compared with their WT counterparts, and the number of CD4+Foxp3+ cells was significantly lower in CCR4−/− mice at 70 days of infection compared with WT mice." (PMID 30584243, 2018).
infection (continued). "A recent study has reported that depletion of CD4+ T cells 4 days after infection did not protect PbA-infected B6 mice from ECM." (PMID 30250468, 2018). "Indeed, increased frequencies of DENV-specific CD4+ and CD8+ T cells were detected in school children who subsequently experienced subclinical infection, in comparison with symptomatic secondary DENV infections." (PMID 29473899, 2018). "The M2e5x VLP group showed a low level of vaccine-induced pre-existing antigen-specific TNF-α+ and IFN-γ+ CD4 T cells resident in the lung tissues and BAL before infection, which can secrete cytokines upon stimulation and rapidly expand during challenge infection." (PMID 29324805, 2018). "Nevertheless, these results collectively indicate that an acute, vaccine-induced increase in CD4+ lymphocytes relative to CD8+ cells in CD134+SU immunized cats may contribute to viral integration and the establishment of FIV infection." (PMID 29736270, 2018). "Although some non-transgenic CD4+ T cells also acquire an activated phenotype upon infection, the fold-change is higher in the P25 transgenic cells in comparison to the non-transgenic (2.05±0.21 vs. 1.48±0.34, p<0.0001 by Student t-test)." (PMID 29499041, 2018). "There were almost no CD4-CD8+PS+ CTL and very few CD4+CD8+lowPS+ CTL at any time point after target cell infection." (PMID 30188946, 2018). "Despite non-transgenic cells become also enriched with IFNγ+ cells upon infection, a higher percentage of P25 transgenic than non-transgenic CD4+ T cells producing cytokines is detected." (PMID 29499041, 2018). "Considered altogether, these results demonstrate that the Envs studied here are not adapted to infection of cells expressing low levels of CD4." (PMID 30521629, 2018). "Importantly, conventional CD4+ and CD8+ T cells migrate into the liver as early as day 3 post infection and this response peaks during days 5–7 (Lenzet al., 1996;Unanue, 1997)." (PMID 29862325, 2018). "To our knowledge, IL-27 mediated restriction of a cytotoxic program in antiviral CD4 T cells has not been described before and we sought to identify the relevant cellular source for this new role of IL-27 during infection." (PMID 30044874, 2018). "Taking into account the use of TA-AgNPs as microbicides, we can therefore conclude that upon treatment of primary infection, AgNPs-treated HSV-2 may be effectively internalized by migratory DCs, activate them to present and prime CD4+ and CD8+ T cells." (PMID 29872440, 2018). "In contrast to wild-type littermates (CD4-Cre+/+ MALT1FL/FL), infection of T cell-specific MALT1−/− mice (CD4-Cretg/+ MALT1FL/FL) with ERA virus led to severe disease and death between 15 and 17 dpi, similarly to the phenotype observed in MALT1 full-knockout mice." (PMID 29367251, 2018). "The fact that cytokines enhance viral replication but, more importantly, promote the infection of resting CD4+ T-cells is not new." (PMID 29997630, 2018). "In our cohort, low memory pTfh cell frequencies correlated with decreased %CD4 and CD4:CD8 ratios and increased HIV viral load, which may reflect preferential infection of Tfh cells by HIV." (PMID 30197641, 2018). "However, in the αβT cell fraction, both CD4+ and CD8+ T cells increased during the initial 6 d of infection and decreased thereafter." (PMID 30619302, 2018). "HIV binding is mediated via CD4 and chemokine co-receptors, but this does not explain the preferential infection of central memory CD4+ T cells." (PMID 30026537, 2018). "However, since Tip-DCs were also observed to exhibit T-cell stimulatory capacity in different infection models, the intrinsic ability of Tip-DCs derived from TLR2 and/or TLR9 KO mice to stimulate CD4+ and CD8+ T cells remains to be investigated." (PMID 29760708, 2018). "We demonstrate the importance of FC-rich cells and lipid rafting for DC-SIGN-mediated endocytosis of HIV-1 and subsequent trans infection of CD4+ T cells observed in PR that is lacking in NP." (PMID 29643243, 2018).